INS (insulin)
Diseases named in the same sentence as INS in open-access papers (continued):
Sharing a sentence is not in itself a finding about the gene and the disease.
diabetes (continued). "Larger islets are reported as better functioning in terms of insulin secretion, which may have a protective effect on diabetes." (PMID 40809458, 2025). "Additionally, since insulin and IGF-1 signaling associated with diabetes has been reported to be involved in the molecular mechanism of osteosarcopenia, it is possible that similar signaling is also involved in osteodynapenia." (PMID 39894806, 2025). "During streptozotocin (STZ)‐induced diabetes stress in pancreatic β‐cells, Foxo3a inhibits Parkin‐mediated mitochondrial recruitment and mitophagy, thereby impacting the growth of pancreatic β‐cells and insulin secretion." (PMID 39413003, 2025). "Diabetes is a complex, chronic endocrine disorder, characterized by elevated blood glucose levels due to insufficient insulin production, or the body’s inability to use insulin effectively." (PMID 40574043, 2025). "Therefore, considerable reductions and rapid adjustments in insulin doses should be anticipated when starting tirzepatide in individuals living with AS and diabetes mellitus on concomitant insulin therapy." (PMID 40302276, 2025). "Hyperglycemia and other metabolic abnormalities associated with diabetes activate the NF-κB pathway, leading to the overproduction of pro-inflammatory cytokines like TNF-α and IL-6, which interfere with insulin signaling giving rise to mutual amplification of inflammation." (PMID 40136728, 2025). "Additionally, managing diabetes in children requires comprehensive healthcare resources, including regular monitoring, insulin therapy, and education on lifestyle modifications." (PMID 40217667, 2025). "Diabetes was present in 13.2% of patients, with 10.5% being insulin-dependent." (PMID 39964666, 2025). "Based on these observations, we propose that the cognitive decline observed in the diabetic group, alongside reduced NPTX2 levels, may be partially attributed to decreased insulin levels and/or impaired insulin function commonly seen in diabetes patients." (PMID 40694319, 2025). "Whilst the vast majority of patients with diabetes have type 2 diabetes whose treatment may include insulin, there are an appreciable proportion of patients with type 1 diabetes in Ghana whose treatment is based solely on insulin therapy." (PMID 39854487, 2025). "In situations involving diabetes, the external administration of insulin is crucial." (PMID 40574088, 2025). "Given that impaired GLP-1 secretion is closely associated with the pathophysiology of type 2 diabetes mellitus (T2DM), regular dietary incorporation of PBR may offer dual benefits: improving insulin sensitivity and enhancing endogenous incretin responses." (PMID 40509433, 2025). "Glucose and insulin metabolism in patients with diabetes are profoundly altered by advanced CKD." (PMID 40352967, 2025). "For example, systems are being developed to detect heart attacks early by monitoring electrochemical signals, manage diabetes through automated insulin dosing, and accelerate healing with smart wound dressings that release drugs in response to infection or inflammation." (PMID 40428648, 2025). "Similarly, sclerostin, secreted by osteocytes, is highly secreted in patients with diabetes and leads to compromised glucose tolerance and insulin sensitivity." (PMID 40149867, 2025). "Due to the recent focus on GLP-1 and its analogues for treatment, our present study suggests a new possibility for Oxt to induce internal intra-islet GLP-1 secretion, which may enhance insulin secretion and thus hold potential for diabetes treatment." (PMID 40317718, 2025). "In such cases, adjustments to insulin dosages are managed promptly, and regular doctor consultations—whether through home visits or video calls—are included in a chronic diabetes management package." (PMID 40547053, 2025).
diabetes (continued). "Checking insulin expiry was significantly associated with duration of diabetes (p < 0.001), insulin therapy duration (p = 0.041), and age (p = 0.020), but not with the type of insulin delivery device (p = 0.062)." (PMID 41306599, 2025). "As the duration of diabetes increases, the patient’s insulin function declines." (PMID 41244780, 2025). "In 1975, Cudworth and Woodrow first described an association of HLA antigens with juvenile-onset and/or insulin-dependent, but not insulin-independent, forms of diabetes." (PMID 40553147, 2025). "Thus, continuous monitoring of the glucose level, with concomitant insulin medication, is the only solution for diabetes." (PMID 41002316, 2025). "This is why this type of diabetes is considered insulin-dependent." (PMID 40265815, 2025). "Most participants had a diabetes duration of less than 10 years and were new to insulin therapy." (PMID 41476921, 2025). "Extracted data included metabolic outcomes (glycated hemoglobin A1c (HbA1c), glycemic variability (GV), insulin dose (ID), lipids, blood pressure, body weight, and others), as well as psychosocial indicators (i.e., quality of life, diabetes-related stress, and fear of hypoglycemia)." (PMID 41228423, 2025). "Bitter melon may be a useful supplement to promote energy balance and improve glucose homeostasis, potentially reducing some of the insulin resistance and glucose transport problems typical in diabetes." (PMID 40184394, 2025). "In summary, preclinical studies strongly indicate that NS and its bioactive compounds, especially thymoquinone, may improve diabetes through antioxidant, anti-inflammatory, and insulin-sensitizing effects." (PMID 41302106, 2025). "Additionally, Pathway enrichment profiling identified key lipid metabolism-related signaling cascades: JAK–STAT, TGF-β, FoxO transcriptional regulation, insulin signaling, adipocytokine communication, and diabetes pathways." (PMID 40535017, 2025). "Oxidative stress leads to pancreatic cell death, contributing to insulin depletion in diabetes." (PMID 40149100, 2025). "According to the American Diabetes Association (ADA) standards of care, other types of treatments and practices are recommended in conjunction with standard insulin therapy; Pramlintide (amylin analogue) is sometimes indicated for patients on insulin therapy." (PMID 39607902, 2025). "The regulations have influenced the growth and sophistication of combination products as we have seen in the form of insulin pumps to manage diabetes, drug-coated dressings for improved wound healing, and more recently drug-vaccine inhalers and wearable drug delivery devices." (PMID 41383269, 2025). "Type 2 diabetes mellitus (T2DM) is a disease caused by a combination of insulin resistance, the body’s inability to properly utilize insulin, and a decline in the body’s ability to secrete insulin." (PMID 41464936, 2025). "This article reports on the diagnosis and treatment process of a 12-year-old patient with diabetes complicated by pulmonary mucormycosis, in which mNGS rapidly confirmed Rhizopus infection and nebulized amphotericin B combined with intensified insulin therapy achieved clinical stability." (PMID 41585813, 2025). "Genes related with insulin secretion may influence the phenotype of diabetes differentially and different genes may be working on different steps of T1D development." (PMID 40244115, 2025). "A case study involving 324 individuals with insulin-treated type 2 diabetes mellitus (T2DM) demonstrates the utility of QoCGM, highlighting the distinct aspects of glucose dynamics captured by different CGM-derived metrics through an analysis of their coefficients of determination (R2)." (PMID 40511383, 2025). "In addition, enriched KEGG pathways in Pax6os1-silenced MIN6 cells included “insulin secretion,” “maturity onset diabetes of the young,” and “type II diabetes mellitus”." (PMID 39811653, 2025).
diabetes (continued). "Thus, even when an individual is ‘perfectly’ managing their diabetes, blood glucose levels can be volatile, creating a context of significant unpredictability, especially for those taking exogenous insulin." (PMID 40564574, 2025). "In another cohort study that included 1.651.452 patients with diabetes who were prescribed GLP-1 RAs, insulin, or metformin, GLP-1 RA use was associated with a significant risk reduction in 10 obesity-associated-cancers, including HCC (HR, 0.47; 95%CI, 0.36–0.61), compared to insulin use." (PMID 40149352, 2025). "A recent meta-analysis demonstrated that increased insulin levels and hyperglycemia, even in individuals without diabetes, are associated with heightened cardiovascular risk." (PMID 40564010, 2025). "Exact mechanisms behind a higher risk of new-onset diabetes following COVID-19 infection are not yet clear, however, insulin resistance has been proposed as a central mechanism." (PMID 40901355, 2025). "Considering the well-documented importance of controlling high peak glucose levels in the management of diabetes, these preliminary findings indicate the potential utility of RL to modulate postprandial blood glucose and insulin levels in response to carbohydrate intake, in this case sucrose." (PMID 40944237, 2025). "KLK1 therapy has been studied in type 2 diabetes mellitus due to its role in the kallikrein‐kinin system, which influences insulin sensitization and glucose homeostasis by enhancing insulin‐induced glucose uptake, glucose transporter 4 translocation, and insulin receptor signaling." (PMID 40237565, 2025). "In this study, we demonstrated that, compared with the controls, male C57BL/6 mice increase body weight significantly, become insulin resistant, glucose-intolerant, and change expression of diabetes-related gene of interest in the pancreas and other glucose-regulatory tissues after 12 weeks of a WD." (PMID 41614817, 2025). "Clinical data showed that as estrogen levels declined, the overall fat mass of menopausal females began to increase, and the sensitivity of peripheral tissues to insulin decreased, resulting in a rapid increase in the incidence of diabetes and cardiovascular disease." (PMID 40647233, 2025). "For recipients with undiagnosed diabetes or a history of oral antidiabetic medication use, a fixed dose of intermediate‐ or long‐acting insulin may initially be considered to manage glucocorticoid‐induced hyperglycaemia." (PMID 40931439, 2025). "By integrating findings from electrophysiological, molecular, and clinical studies, this review provides a balanced perspective on RyRs in islet cell physiology and pathology, emphasizing their significance in both normal insulin secretion and current diabetes therapies." (PMID 40422193, 2025). "This analysis highlighted Alzheimer’s disease (seven times), Parkinson’s disease (six times), diabetes mellitus (four times), hypertension (four times), inflammation (three times), schizophrenia (two times), heart diseases (two times), and insulin resistance (two times)." (PMID 40732226, 2025). "Regarding bolus insulin treatment, individuals with LADA had the highest percentage of bolus insulin prescription (72.1%), followed by T1DM (71.3%), T2DM (10.1%) and GDM (2.6%), with more fCGM users being prescribed bolus insulin than those who perform BGM in all types of diabetes, except LADA." (PMID 39901274, 2025). "Overall, these results suggest that both HQS and the AC could enhance insulin sensitivity in mice with diabetes and facilitate the regeneration of impaired islet β cells." (PMID 40429723, 2025). "Insulin infusions may stimulate LPL activity and lower TG levels in patients with insulin-deficient diabetes presenting with HTG due to insulin deficiency but are ineffective in those with complete LPL deficiency and can cause hypoglycemia." (PMID 41378317, 2025).
diabetes (continued). "The same integrated personalised diabetes management program was analyzed in a one-arm study with American T1D and T2D patients who are treated with insulin and showed the same average reductions after 6 months of 0.5% ± 0.6% (p = 0.045, d = 0.81) for patients in specialist care settings." (PMID 40661654, 2025). "Consequently, we proceeded to explore the expression of intersection genes of differential genes in m6A modification sites and differential mRNAs in people with diabetes before and after intensive insulin therapy." (PMID 40299682, 2025). "The tailored release of insulin through gelatin-based systems ensures that it is delivered in a manner that closely mimics the body’s natural insulin production and secretion, providing a more personalized approach to diabetes treatment." (PMID 40352348, 2025). "However, the persistence of hyperglycemia beyond the neonatal period and requirement for ongoing insulin therapy argued against transient neonatal diabetes." (PMID 41393705, 2025). "Additionally, genetic mutations in factors involved in β-cell differentiation, insulin biosynthesis, and insulin secretion can also lead to diabetes." (PMID 40666490, 2025). "This hypothesis is supported by the notion that the regeneration of pancreatic β-cells damaged by diabetes mellitus through BCS leads to improved insulin secretion in response to increased blood glucose levels." (PMID 40002361, 2025). "After adjusting for classical diabetes risk factors, the associations between HS with lower metabolic syndrome (Mets-BMI), hepatic insulin resistance (HOMA-IR), CRP and increased whole body insulin sensitivity (MATSUDA) remained significant." (PMID 41276872, 2025). "Research on molecular and mechanical glucose-responsive insulin could revolutionize diabetes care, but these concepts remain largely theoretical at the moment." (PMID 40137145, 2025). "Caffeic acid reduces blood glucose and reveals a protective effect against diabetes; quinic acid increases mitochondrial Ca2+ and stimulate insulin secretion in pancreatic beta‐cells; chlorogenic acid has a protective effect on pancreatic beta‐cells and blood glucose control." (PMID 40518509, 2025). "As the global prevalence of diabetes continues to escalate, there is a growing interest in identifying safe and effective dietary interventions that can aid in the regulation of glucose metabolism and enhance insulin sensitivity." (PMID 40572453, 2025). "In addition, potential associations between pathway activation and clinical outcomes are explored, including tumor stage, patient survival, and metabolic parameters such as diabetes, use of oral antidiabetic drugs, insulin therapy, and hemoglobin A1c levels." (PMID 41397158, 2025). "Diabetes mellitus is a chronic metabolic condition characterized by hyperglycaemia, resulting from either insufficient insulin production or the body’s inability to respond effectively to insulin." (PMID 40958722, 2025). "Notably, participants classified as Pre_IIc show lower FPG and PG120 levels but displayed β-cell dysfunction and insulin deficiency, evident through lower fasting and postprandial serum insulin levels, indicating a role in the pathogenesis of diabetes." (PMID 40191259, 2025). "It has been shown that although glucagon has these effects, the glucose response to glucagon in individuals with insulin-treated diabetes is highly variable, influenced by the levels of insulin and the ratio of insulin to glucagon in the body, along with the timing of the most recent injection." (PMID 41510436, 2025). "The key finding from this study is that dogs with clinically stable, insulin‐treated, spontaneous diabetes mellitus had decreased serum lipids (including total triglycerides, total cholesterol, and %TRL) and LPS after 21 days of fenofibrate therapy, while HDL amounts (AUC) and %HDL both increased." (PMID 40384217, 2025). "Clinical types of diabetes and how they map to insulin therapy." (PMID 40035222, 2025).
diabetes (continued). "Indeed, the idea of low-carbohydrate diets as a treatment for T1DM is older than a century, and starvation diets were the mainstay of diabetes treatment in the pre-insulin era." (PMID 40573112, 2025). "This suggests that the emergence of AMR in the context of diabetes may only result when insulin signaling is sufficiently impaired and that even moderate control of diabetes may curb potential AMR emergence." (PMID 39937900, 2025). "Items with p < 0.05 were included in the model analysis (because the ACCI score included whether there was diabetes, we used ACCI instead of “diabetes” and “using insulin/diabetic drugs”)." (PMID 41018204, 2025). "Thus, the PPARy pathway is an important target for promoting protection from insulin-resistant states and the development of diabetes." (PMID 41472730, 2025). "Conversely, restoring hypothalamic insulin action can prevent diabetes." (PMID 39966707, 2025). "This might look like, for example, counting carbohydrates, checking blood glucose, and dosing insulin according to one’s prescribed regimen, even while experiencing diabetes distress, fear of hypoglycemia, and other psychological reactions." (PMID 40564574, 2025). "A meta-analysis of forty-six randomized controlled trials showed that probiotics and synbiotics administration reduced fasting plasma glucose, hemoglobin A1c, insulin serum levels, and insulin resistance in patients with prediabetes and type 2 diabetes mellitus." (PMID 40284576, 2025). "Hypoglycaemia is a common complication of diabetes therapy, particularly in individuals treated with insulin or insulin secretagogues such as sulfonylureas; however, hypoglycaemia does not impact BMD, but bone fractures may result from falls." (PMID 41373586, 2025). "Higher intakes of saturated fat may also impair insulin signaling, contributing to insulin resistance, hepatic steatosis, obesity, and type 2 diabetes mellitus." (PMID 40077611, 2025). "Chalcones like xanthohumol, 4-hydroxyderricin, and isoliquiritigenin exhibit strong inhibitory effects on diabetic markers and have shown positive results in reducing blood glucose levels, improving insulin sensitivity, and protecting against diabetes-related oxidative stress and inflammation." (PMID 40599794, 2025). "The recommended treatment for diabetes is usually a combination of drugs, which may include insulin." (PMID 39957999, 2025). "Since β-cells depend on mitochondrial metabolism to couple glucose sensing with insulin release, restoring their metabolic function could be crucial in preventing diabetes progression." (PMID 41227341, 2025). "All patients with diabetes were on an intense insulin treatment regimen." (PMID 39453571, 2025). "In addition to insulin replacement, protecting and preserving β‐cell function is crucial for long‐term diabetes management." (PMID 40919135, 2025). "Exercise interventions are a recommended method of diabetes management through which patients can achieve blood glucose control, increase muscle volume, and improve insulin sensitivity, while also improving blood lipids, blood pressure, and cardiovascular health." (PMID 40391012, 2025). "It has been suggested that these fabaceous plants can help prevent or reduce the complications of diabetes treatment and may even have similar effects to insulin." (PMID 39861134, 2025). "In addition to nutrition, exercise, medications, and insulin therapy, diabetes education is a crucial part of the treatment plan." (PMID 39961987, 2025). "Overall, these findings suggest that patient knowledge and adherence to insulin administration practices are largely influenced by the length of their diabetes history, duration of insulin therapy, and age, whereas the type of insulin delivery device does not appear to play a major role." (PMID 41306599, 2025).